SLC7A11 (solute carrier family 7 member 11)
Diseases named in the same sentence as SLC7A11 in open-access papers (continued):
Sharing a sentence is not in itself a finding about the gene and the disease.
cancer (continued). "The results showed that SLC7A11 expression is negatively associated with CD8+ T-cell infiltration in seven cancers (DLBC, ESCA, HNSC, LUAD, LUSC, TGCT, and THCA), suggesting the combination of ferroptosis induction and immunotherapy may be suitable in these cancers’ treatment." (PMID 34938318, 2021). "Interferon gamma (IFNγ) released from cytotoxic T cells activates the JAK–STAT1 pathway, which in turn downregulates the expression of SLC7A11 and SLC3A2 inducing ferroptosis in cancer cells." (PMID 34485382, 2021). "To date, four distinct amino acid transporters have received increasing attention for their role in the promotion of cancer: SLC1A5 (also known as ASCT2), SLC7A5 (also known as LAT1), SLC7A11 (also known as xc−), and SLC6A14 (also known as ATB0,+)." (PMID 33806675, 2021). "SLC7A11 expression in tumors was found to negatively correlate with CD8+ T cell counts and IFNγ expression in tumors, and prognosis of cancer patients." (PMID 33891303, 2021). "In addition, SLC7A11 was reported to promote cystine uptake and glutathione biosynthesis, resulting in protection from oxidative stress and ferroptosis, a form of controlled iron-dependent cell death that is attracting increasing attention as a new option for cancer therapy." (PMID 34200770, 2021). "We also analyzed the prognostic values of SLC7A11, GPX4, and AIFM2 in pan-cancer using Kaplan–Meier database." (PMID 34722530, 2021). "Four amino acid transporters have been found to be highly expressed in cancer, namely SLC7A5, SLC7A11, SLC1A5 and SLC6A14." (PMID 33849550, 2021). "Inhibition of BRD4 by (+)-JQ1, inhibit histone methyltransferase G9a or enhance the histone deacetylase SIRT1 to inhibit BRD4, downregulate GPx4, SLC7A11, SLC3A2 gene expression, regulate ferritinophagy, and induce ferrroptosis in cancer cells." (PMID 34226536, 2021). "Previous work has suggested that altered expression of key negative regulators of ferroptosis including SLC7A11 and GPX4 has a significant bearing on cancer progression." (PMID 34803511, 2021). "Treating tumors with the combination of HGF and anti-IFN-γ agents restored the expression of SLC3A2 and SLC7A11, which suggested that the positive role of IFN-γ in cancer cellular ferroptosis." (PMID 34593794, 2021). "Solute carrier family 7 member 11 (SLC7A11), the cystine/glutamate antiporter, is known as a ferroptosis executor that exhibits a positive correlation with carcinoma progression because of antioxidant function." (PMID 34722314, 2021). "Recent work showed that hypoxia upregulated xCT SLC7A11 expression and increased intracellular cystine levels and GSH synthesis in multiple types of cancer cells." (PMID 31218894, 2020). "SLC7A11 is an essential BAP1 target in human cancers, and BAP1 represses SLC7A11 expression via reducing H2Aub occupancy on SLC7A11 promoter in a deubiquitinating-dependent manner." (PMID 33425217, 2020). "xCT, also known as solute carrier family 7 member 11 (SLC7A11), the light chain of the cystine/glutamate antiporter, is positively correlated with cancer progression due to antioxidant function." (PMID 32630312, 2020). "Data from the DepMap database show high expression levels of SLC1A5, SLC7A11, SLC38A2, and SLC7A5 in the selected cancer cell lines." (PMID 33400734, 2020).
cancer (continued). "One nutrient transporter frequently overexpressed in human cancers is the cystine/glutamate antiporter solute carrier family 7 member 11 (SLC7A11; also known as xCT)." (PMID 29764521, 2018). "To date, two amino acid transporters have been found to be over-expressed in cancers: SLC7A5 and SLC7A11." (PMID 30558624, 2018). "Notably, these studies were conducted in a wide variety of cancer cell lines across various cancer types, including breast, cervical, kidney, and brain cancers, as well as mesothelioma, suggesting a universal role of SLC7A11 in regulating glucose starvation-induced cell death." (PMID 29764521, 2018). "In this context, SLC7A11 expression was also dependent on the transcription factor ATF4, which is known to cross talk with NRF2 in cancer cell metabolism." (PMID 28967864, 2017). "In KRAS-mutant cancers with G12Ci-resistant cells, SOX2, SLC7A11 and SLC40A1 are downregulated." (PMID 41516092, 2025). "In summary, this review highlights the pivotal role of SLC7A11 as a non-conventional checkpoint in the pathogenesis of cancer, primarily through its regulation of ferroptotic responses under a spectrum of stress conditions." (PMID 39569390, 2025). "Furthermore, we examined the expression of several key ferroptosis-related proteins in radioresistant cancer cells, including GPX4, SLC7A11, Nrf2, TfR1, and ACSL3." (PMID 40102409, 2025). "m6A methylation 5′UTR and 3′UTR regions regulate mRNA degradation of SLC7A11 in cancer cells, while there is no m6A modification in SLC7A11 mRNA according to our data." (PMID 39800682, 2025). "High SLC7A11 levels in NPC cells led to reduced MHC-I antigen presentation by limiting TAP1 transcription and activating ERAD-dependent MHC-I degradation, which can hinder the recognition of cancer cells by the immune system." (PMID 39820491, 2025). "All these data indicated that GATA3 was involved in the negative effects of METTL3 on transcription of SLC7A11 and ferroptosis activity of cancer cells." (PMID 39800682, 2025). "Additionally, knockout or inhibition of solute carrier family 7 member 11 (SLC7A11) can induce ferroptosis, leading to the selective death of CRC cancer stem cells." (PMID 41278282, 2025). "The expression of SLC7A11 has been found to have a negative correlation with the infiltration of CD8+T cells in several types of cancers, including DLBC, ESCA, HNSC, LUAD, LUSC, TGCT, and THCA." (PMID 39820491, 2025). "This aligns with reports that STAT3 represses SLC7A11/GPX4 in non-malignant settings but promotes ferroptosis resistance in cancer." (PMID 41515376, 2025). "Our data indicate that METTL3 controls SLC7A11 transcription through GATA binding protein 3 (GATA3) and H3K27 lysine demethylase 6B (KDM6B), highlighting a potential approach for cancer therapy by disrupting m6A-regulated ferroptosis in cancer cells." (PMID 39800682, 2025). "It seems that the System xc- plays and important role during F. nucleatum infection in cancer cells, because the bacterium significantly promoted L-Glutamate efflux from HSC3 and the expression of SLC7A11 in HSC3 cells, but when an inhibitor of this antiporter was applied, the effects were reverted." (PMID 39743544, 2025). "Cancer cells can resist ferroptosis by upregulating the expression of antioxidant enzymes, such as GPX4, and iron regulatory proteins, such as solute carrier family 7 member 11 (SLC7A11), thereby enhancing their survival." (PMID 40615369, 2025). "This study reveals a mechanism by which USP5 regulates SLC7A11 independently of the ubiquitin system, expanding the regulatory network of SLC7A11 and further highlighting the heterogeneity of DUB functions in different cancers." (PMID 41213937, 2025).
cancer (continued). "In conclusion, our comprehensive pan-cancer analysis research has demonstrated the significant prognostic and immunological role of disulfidoptosis across a spectrum of tumors, notably HCC, and identified SLC7A11 as a promising therapeutic target." (PMID 38397869, 2024). "Similarly, the significantly downregulated genes included CHAC1, SLC7A11, PYCR1, PSPH, and DDIT4, among others, with these genes being involved in iron death, cancer cell expansion, and apoptosis (15, –, 19)." (PMID 38299864, 2024). "These include inhibition of PUFA‐PLs synthesis and peroxidation, restriction of labile iron availability, and upregulation of cellular defense systems such as SLC7A11, GPX4, and FSP1, all of which enable cancer cells to bypass ferroptosis and continue proliferating." (PMID 39568772, 2024). "Initially, the expression level of SLC7A11 in certain cancer cells was markedly higher than that in normal cells." (PMID 38886311, 2024). "Of note, both SLC7A11 and SLC3A exhibited marked differential expression across almost all cancers." (PMID 38397869, 2024). "Additionally, we confirmed the downregulation of SLC7A11 mRNA in viable cancer cells with SNF2L deletion, whereas SLC7A11 mRNA was elevated in HCCLM3 cells overexpressing SNF2L." (PMID 39532848, 2024). "Indeed, specific agents such as erastin (an SLC7A11 inhibitor) and RSL3 (a GPX4 inhibitor) can trigger ferroptosis, selectively eliminating cancer cells." (PMID 38799433, 2024). "Thus, OC cells protect themselves by developing antioxidant responses, such as upregulating Solute Carrier Family 7 Member 11 (SLC7A11), leading to changes in cysteine import to cancer cells and maintaining redox homeostasis." (PMID 39195233, 2024). "Additionally, oxidative stress levels are elevated in cancer cells, which is compensated by the upregulation of antioxidant factors like ferroptosis suppressor protein-1 (FSP-1), solute carrier family 7 member 11 (SLC7A11) and glutathione peroxidase 4 (GPX4)." (PMID 38603713, 2024). "Therefore, we first analyzed the differential expression of GPX4 and SLC7A11 using the TAGG database and found that both were highly expressed in cancer patients." (PMID 39668836, 2024). "SLC7A11, as an essential amino acid transporter that promotes cysteine supply and GSH synthesis, is a core regulator of the cellular ferroptosis defense system and is a promising therapeutic target in cancer therapy." (PMID 38987730, 2024). "Furthermore, overexpression of the cancer stem cell marker CD44 promotes the interaction between OTUB1 and SLC7A11, reducing SLC7A11 degradation and inhibiting ferroptosis." (PMID 39769177, 2024). "Treatment with glucose transporter (GLUT) inhibitors can induce disulfidptosis in cancer cells with high SLC7A11 expression without significant toxicity to normal tissues, thus effectively inhibiting tumor growth." (PMID 38840910, 2024). "Subsequent research corroborated the significance of converting glutamate to α-KG for the survival of cancer cells in the absence of glucose, highlighting the regulatory function of SLC7A11 in modulating the metabolic adaptability of cancer cells." (PMID 39040097, 2024). "Notably, both SLC7A11 and SLC3A1 demonstrated marked differential expression across almost all cancer types." (PMID 38397869, 2024). "Cancer cells upregulate multiple amino acid transporters as a means to increase the influx of amino acids from circulation; this includes the transporters SLC7A5 (LAT1), SLC1A5 (ASCT2), SLC6A14 (ATB0,+), SLC7A11 (x-c), SLC38A5 (SNAT5) and SLC43A2." (PMID 36765717, 2023). "Similarly, in breast cancer, expression of SLC7A11 and GPX4 were elevated, which were found to play a critical role in promoting cancer cell survival and resistance to ferroptosis." (PMID 37266741, 2023).
cancer (continued). "Some studies have explored the roles of SLC7A11, CAPG, and SQSTM1 in cancer." (PMID 37198416, 2023). "Considering SLC7A11 is critical for the uptake of cystine and synthesis of GSH, we tested if UTP11 might affect GSH levels in cancer cells." (PMID 37087976, 2023). "In addition, TGF-β1 (transforming growth factor β1) released by macrophages can inhibit the expression of SLC7A11 by activating the SMAD-dependent signaling pathway and finally lead to ferroptosis of cancer cells." (PMID 37880315, 2023). "Inactivation of SLC7A11 or GPX4 with ferroptosis inducers (FINs) can make radioresistant cancer cells and xenograft tumors sensitive to ionizing radiation, indicating the potential significance of radiotherapy combined with FINs in cancer treatment." (PMID 37714846, 2023). "When SLC7A11 is inhibited, BAP1 triggers ferroptosis to partially inhibit cancer progression." (PMID 37210575, 2023). "While it is out of the scope of this review to outline all the complex interconnections between ferroptosis, cancer and drug resistance, we want to point out three promising drug targets at this interface, namely NRF2, SLC7A11, and GPX4, and refer to comprehensive review articles in this field." (PMID 36658724, 2023). "BAP1 inactivation in cancer cells diminishes SLC7A11, leading to tumor ferroptosis resistance without the regulation of NRF2 and ATF4." (PMID 37190313, 2023). "In cancer cells, low concentrations of compound 55 (12.5–100 nM) augmented intracellular ROS and MDA levels, depleted intracellular GSH, and decreased the expression of GPX4, SLC7A11, and SLC40A1." (PMID 36658724, 2023). "Not surprisingly, cancers with glutamine and glucose addiction are sensitive to class I ferroptosis inducers that inhibit SLC7A11." (PMID 38203246, 2023). "We found that treatment with the ROS scavenger Trolox potently suppressed H2O2-induced ROS, but did not affect H2O2-triggered cell death in SLC7A11-high cancer cells." (PMID 37339981, 2023). "Therefore, OTUB1 plays a critical role in stabilizing SLC7A11 and regulates CD44 (cancer stem cell marker)-mediated effects on ferroptosis to promote the development of human cancers." (PMID 37190313, 2023). "By directly binding to SLC7A11, recombinant human autophagy effector protein (BECN1) inhibits the activity of system xc−, promotes GSH consumption and lipid peroxidation, and induces ferroptosis in cancer cells." (PMID 37005430, 2023). "Next, xCT (SLC7A11) protein expression was evaluated in normal epithelium and carcinoma tissues." (PMID 36672272, 2023). "Besides, our research manifested the correlation of SLC7A11 with 8 IC genes, namely CD274 (also known as PD-L1), HAVCR2, LAG3, SIGLEC15, PDCD1LG2, CTLA4, PDCD1, and TIGIT in 33 cancer types." (PMID 36267158, 2022). "It has been shown that amino acid transporters can be regulated by m6A modification, as the main glutamine transporter SLC1A5 in cancer cells can be regulated by the m6A modified demethylase FTO and SLC7A11 is promoted to decay by preferentially bound to YTHDC2." (PMID 35054897, 2022). "In lung cancer, the RNA-binding protein RBMS1 could promote the levels of SLC7A11 and increase the production of GSH, resulting in the inhibition of ferroptosis in cancer cells." (PMID 35342359, 2022). "It has been discovered that SLC7A11 is upregulated in pancreatic ductal adenocarcinomas (PDACs), which enhances cystine absorption and GSH production, hence promoting the development and existence of cancer cells by suppressing ferroptosis." (PMID 35408533, 2022).
cancer (continued). "In conclusion, the potential correlation between SLC7A11 expression patterns and IC gene responses may help understand the therapeutic mechanisms of SLC7A11 in LIHC and other cancer types." (PMID 36267158, 2022). "Suppressing the activity of SLC7A11 via genetic ablation or pharmacologic inhibition affects GSH synthesis, which leads to the accumulation of lipid peroxidation products, ultimately inducing ferroptosis in cancer cells." (PMID 35522946, 2022). "In an environment lacking micronutrient levels, cancer cells can regulate the function of SLC7A11 by mTORC2-mediated phosphorylation to protect themselves from cellular stress that facilitates increasing glutamate efflux and cystine uptake." (PMID 36552652, 2022). "Cancer cells require large amounts of cysteine and GSH to neutralize the increased intracellular ROS, and the nutrient dependency generally needs to be the increased function of SLC7A11." (PMID 36552652, 2022). "Although sorafenib can induce ferroptosis in cancer cells, the expression levels of SLC7A11 did not affect the treatment efficacy of sorafenib." (PMID 34761566, 2021). "Indeed, environmental cystine availability increases glutamine anaplerosis through Cystine/glutamate transporter (xCT)/solute carrier family (SLC) 7A11 and enhances the efficacy of glutaminase inhibition in cancer cells." (PMID 33401771, 2021). "It was shown that activated CD8+ T cells secrete IFNγ during immunotherapy, which down-regulates the expression of SLC7A11 (as well as its regulatory partner SLC3A2) and subsequently inhibits cystine uptake in cancer cells, thereby augmenting lipid peroxidation and ferroptosis." (PMID 33891303, 2021). "We have shown that cancer cells that overexpress both SLC7A11 and SLC3A2 are the ones that should be considered xCT-positive, and that this pathway, through the selenocysteine biosynthesis pathway mediated production of GPX4, impacts a cancer cell’s sensitivity to various ferroptotic inducers." (PMID 33672555, 2021). "Lack of SLC7A11 and knockdown of GPX4 have been demonstrated to increase ROS-mediated lipid peroxidation and induce subsequent ferroptosis in even resistant cancer cells, indicating that deficiency in antiferroptotic function enhances cancer cell death." (PMID 35118067, 2021). "Our study demonstrated that in most cancer types, SLC1A5, SLC7A5, SLC7A11, and SLC3A2 were highly expressed and indicative of poorer survival outcomes, while the effects of changes in the expression of GLS2 and GLS depended on the type of cancer under consideration." (PMID 34573287, 2021). "We also analyzed the mRNA levels of SLC7A11, GPX4, and AIFM2 in pan-cancer using Oncomime database." (PMID 34722530, 2021). "The most studied transporters for their role in cancer include SLC1A5 (alanine–serine–cysteine transporter 2 or ASCT2), SLC7A5 (system L amino acid transporter 1 or LAT1), SLC7A11 (system x−c transporter or xCT), and SLC6A14 (amino acid transporter B0,+ or ATB0,+)." (PMID 34704597, 2021). "Prognostic values of SLC7A11, GPX4, and AIFM2 in pan-cancer in Kaplan–Meier database." (PMID 34722530, 2021). "For example, the cancer stem cell marker CD44 and the deubiquitinating enzyme OTU domain-containing ubiquitin aldehyde binding protein 1 (OTUB1) promote ferroptosis resistance through stabilizing SLC7A11." (PMID 33891303, 2021). "In addition, SLC1A5 (ASCT2), SLC7A5 (LAT1), SLC7A11 (xCT), and SLC6A14 (ATB0+) have been shown to be positively expressed in cancer." (PMID 33937189, 2021). "Not surprisingly, SLC7A11 is often found over-expressed in cancer cells and has been proposed as a novel target in cancer therapy." (PMID 34852841, 2021).